FLI1 (Fli-1 proto-oncogene, ETS transcription factor)
Diseases named in the same sentence as FLI1 in open-access papers (continued):
Sharing a sentence is not in itself a finding about the gene and the disease.
lupus (continued). "Considering the emerging evidence that the CXCL10-CXCR3 axis plays a critical role in lupus and other inflammatory/autoimmune diseases, our results provide additional insight in defining the mechanisms by which FLI-1 modulates inflammation and disease development." (PMID 37790939, 2023). "Friend leukemia virus integration 1 (Fli-1), a member of the E26 transformation-specific (Ets) transcription factor family, plays a key role in the pathogenesis and development of various diseases including lupus, cancer, systemic sclerosis and sepsis." (PMID 37790939, 2023). "Likewise, kidneys from Fli-1+/− lupus-prone NZM2410 mice displayed significantly fewer inflammatory infiltrates compared to the Fli-1+/+ NZM2410 controls." (PMID 32183259, 2020). "In addition to cancer, Fli-1 affects various human autoimmune diseases including Systemic Lupus Erythematosus (SLE) and Systemic sclerosis/scleroderma." (PMID 28052010, 2017). "Together, our results in the T cells from early disease lupus mice suggest FLI1 controls directly or indirectly the transcription of Neu1 such that reduction of FLI1 leads to decreased Neu1 expression/activity leading to decreased TCR-specific activation and IL-4 production." (PMID 24040398, 2013). "However, the specific effects of reducing FLI1 on lupus T cell function in disease pathogenesis remain uninvestigated." (PMID 24040398, 2013). "In summary, our results demonstrate a role for FLI1 in regulating lupus T cell activation and IL-4 production through modulation of glycosphingolipid metabolism, specifically by mediating the breakdown pathway through the control of Neu1 expression and/or NEU activity during early disease." (PMID 24040398, 2013). "Reducing the expression of FLI1 or targeting the glycosphingolipid metabolic pathway in lupus may serve as a therapeutic approach to treating lupus." (PMID 24040398, 2013). "Genetically reducing globally the expression of the ETS transcription factor FLI1 by 50% in two lupus mouse models significantly improves disease measures and survival through an unknown mechanism." (PMID 24040398, 2013). "Furthermore, it was shown that B-lymphocytes from human lupus patients or from lupus erythematous mouse model MRL/lrp displayed increased Fli-1 expression whereas another study showed an up-regulated miR-17-92 expression in mouse models of lupus." (PMID 23056458, 2012). "Together, these studies suggested that a shorter microsatellite in the Fli1 promoter may contribute to over-expression of Fli1 and to the pathogenesis of lupus." (PMID 21087477, 2010). "For example, in scleroderma, reduced expression of Fli1 in skin fibroblasts and endothelial cells is implicated in the fibrotic and vascular components of the phenotype, while in lupus elevated expression of Fli1 in mononuclear cells is thought to contribute to the disease phenotype." (PMID 21087477, 2010). "Furthermore, it was demonstrated that reducing Fli1 levels by 50% in hematopoietic cells in a lupus mouse model also resulted in improved disease and survival." (PMID 21087477, 2010). "Interestingly, globally decreasing Fli1 levels by 50% in two different lupus mouse models resulted in significantly improved disease, most notably improved nephritis, accompanied by significantly prolonged survival." (PMID 21087477, 2010). "We speculate that a reduction in Fli1 promoter activity and, hence, expression may disrupt endothelial cell function in lupus patients and contribute to exaggerated serositis." (PMID 21087477, 2010). "A more precise understanding of how this microsatellite functions to modulate Fli1 expression in different cell types would be beneficial in determining whether this microsatellite may serve as therapeutic marker in lupus." (PMID 21087477, 2010). "This evidence demonstrates that expression levels of Fli1 in lupus affect disease phenotype." (PMID 21087477, 2010).
lupus (continued). "FLI1 can also affect the function of immune cells by regulating cytokines and chemokines and contributes to inflammatory responses in various inflammatory diseases, including sepsis, Alzheimer’s disease, systemic sclerosis, lupus, and graft-versus-host disease." (PMID 39140108, 2024). "Therefore, elevated FLI1 levels in PBMCs among PTSD patients may partially contribute to lupus development." (PMID 39140108, 2024). "Interestingly, peripheral blood lymphocytes from patients with active SLE showed elevated expression of Fli-1 transcripts in parallel with disease activity; elevated levels of Fli-1 were also associated with newly-developed or recurrent lupus nephritis in SLE patients." (PMID 32183259, 2020). "Furthermore, our results suggest that the functional effects of reducing FLI1 on lupus T cells may mediate autoantibody production." (PMID 24040398, 2013). "Importantly, our studies suggest that reducing FLI1 levels and/or inhibiting the glycosphingolipid metabolic pathway, may serve as a therapeutic approach for reducing lupus T cell pathogenesis and treating disease." (PMID 24040398, 2013). "Previous results demonstrated that Fli1 expression is increased in mouse models of lupus and in T cells of SLE patients compared to unaffected controls." (PMID 21087477, 2010). "Based on our results demonstrating that the length of the microsatellite is inversely correlated to Fli1 promoter activity and that a shorter microsatellite is present in lupus-prone mouse strains, we sought to determine whether the length of the microsatellite is associated with SLE." (PMID 21087477, 2010). "Previous studies have shown that Fli-1 is a positive regulator of CCL2, CCL3, CCL4, CCL5, CXCL9, and CXCL10 in the kidneys of Fli-1 heterozygote knockout mice with lupus and CXCL5 in dermal small vessels from Fli-1 knockout mice." (PMID 40305194, 2025). "We showed that globally reducing FLI-1 levels in a lupus prone mouse strain reduced renal Cxcl9 and Cxcl10 gene expression and renal-infiltrating CXCR3+ T cells, and that FLI-1 can upregulate Cxcr3 promoter activity in T cells." (PMID 37790939, 2023). "Nonetheless, we found that the heterozygous state (Fli-1+/−) yielded viable progeny that experienced reduced renal inflammation and prolonged survival in the MRL/lpr mouse lupus model." (PMID 32183259, 2020). "Friend leukemia virus integration 1 (FLI1), an ETS family transcription factor, plays a role in SLE disease progression as demonstrated in two different lupus mouse models." (PMID 24040398, 2013). "Globally reducing the levels of the transcription factor FLI1 in the MRL/lpr and NZM2410 lupus mouse models significantly improves disease by decreasing autoantibody production and increasing survival." (PMID 24040398, 2013). "Reducing FLI1 levels in the MRL/lpr and lupus mouse model resulted in an increase in the percentage of naïve T cells." (PMID 24040398, 2013). "Conversely, reduction of Fli1 levels by 50% in MRL/lpr and NZM2410 lupus-prone mice improved the disease phenotypes in these models by decreasing autoantibody production and kidney disease and significantly prolonging survival." (PMID 21087477, 2010). "The microsatellite-containing region of the Fli1 promoter was amplified and length measured in the Carolina Lupus (CLU) study cohort, MUSC Lupus Clinic (Clinic) study cohort and the SLEIGH study cohort." (PMID 21087477, 2010). "Unlike lupus, expression of Fli-1 was greatly reduced in endothelial and peri-endothelial cells in skin from SSc patients." (PMID 40305194, 2025). "Most importantly, it has been reported that in lupus-prone mice Fli1 expression fails to become down-regulated likely due to aberrant transcriptional regulation." (PMID 25986394, 2015). "We further examined the mechanisms by which FLI1 may be controlling TCR-specific activation and IL-4 production in lupus T cells." (PMID 24040398, 2013).
lupus (continued). "Genetic reduction of FLI1 expression by 50% (Fli1+/-) in NZM2410 and MRL/lpr lupus prone mice significantly decreased autoantibody levels, renal pathology, and proteinuria and significantly increased survival in comparison to lupus mice with wild-type FLI1 levels (Fli1+/+)." (PMID 24040398, 2013). "Transgenic global over-expression of Fli1 in healthy, non-autoimmune prone mice results in a lupus-like phenotype with the presence of autoreactive lymphocytes, autoantibodies and the development of immune complex mediated kidney disease." (PMID 21087477, 2010). "Recently, a GAn polymorphic microsatellite was characterized in the mouse Fli1 promoter that modulates promoter activity and is truncated in two lupus mouse models compared to non-autoimmune prone mice." (PMID 21087477, 2010). "Fli-1′s role in lupus may be partly due to the production of pro-inflammatory mediators such as IL-6 and CCL2, which have been alleviated in endothelial cells and splenic T cells in Fli-1 heterozygous lupus mice." (PMID 40305194, 2025). "We demonstrated previously that a polymorphic microsatellite consisting of GA repeats within the proximal promoter of the mouse Fli1 gene is shorter in the MRL/lpr and NZM2410 lupus mouse models compared to non-autoimmune prone BALB/c and C57BL/6 mice." (PMID 21087477, 2010).
synovial sarcoma (17 papers, 2010 to 2025). "In this study, histology‐specific fusion genes were identified in nine cases, including SYT::SSX1 in synovial sarcoma, EWSR1::FLI1 in ES, and EWSR1::NR4A3 in EMC." (PMID 40755265, 2025).
angiosarcoma (16 papers, 2008 to 2025). A malignant tumor arising from the endothelial cells of the blood vessels. "Angiosarcoma’s synthesis of Fli-1 and ASCCs cytoplasmic immunoreaction for the γ2-chain of ln-5 are their respective distinctive characteristics." (PMID 39006677, 2024). "Expression of at least one of the endothelial markers including CD31, CD34, factor VIII and FLI-1, is required to confirm the diagnosis of angiosarcoma." (PMID 22208720, 2011). "Expression of Fli-1 in angiosarcoma and cellular immunoreaction for ln-5 in ASCC are worked out as distinguishing features of both entities." (PMID 18671846, 2008). "Expression of Fli-1 in angiosarcoma and cytoplasmatic immunoreaction for γ2-chain of ln-5 in ASCC are worked out as distinguishing features of both entities." (PMID 18671846, 2008). "Considering the current hypothesis that angiosarcomas originate from blood vessel and lymphatic endothelial cells, the expression of endothelial markers such as FLI1, ERG, CD31, and CD34 becomes pivotal." (PMID 38902365, 2025). "Thus, combinations of one or more of these vascular markers [CD31, CD34, ERG, and FLI1], along with other immunomarkers are required for prompt and accurate diagnosis of angiosarcoma." (PMID 39845895, 2024). "Fli-1 in angiosarcoma and ln-5 in ASCC are distinguishing features." (PMID 18671846, 2008). "Fli-1 immunoreactivity was only recognized in angiosarcoma (Figure." (PMID 18671846, 2008). "Immunohistochemistry for FLI-1 will be positive, and MYC can be positive in cases of radiation- or lymphedema-induced angiosarcomas." (PMID 40895846, 2025). "Epithelioid angiosarcoma was diffusely and strongly positive for vascular markers, CD31, Factor VIII, and Fli-1, as well as for keratin." (PMID 35001360, 2022). "Histologic evaluation of the polyps was indicative of angiosarcoma, and the diagnosis was eventually confirmed by immunohistochemical analysis with positive CD31, ERG, and FLI1 stains." (PMID 34150400, 2021). "Although Fli-1 can be also rarely identified in carcinomas, ASCC is immunonegative for this marker, so that Fli-1 can be recommended to discriminate between Angiosarcoma and ASCC." (PMID 18671846, 2008). "Although there is no pathognomonic immunohistopathological profile, angiosarcomas stain positive for at least one of the following endothelial cell markers: CD34, CD31, ERG, FLI1, and factor VIII-related antigen." (PMID 40255814, 2025).
systemic sclerosis (16 papers, 2014 to 2025). A chronic disorder, possibly autoimmune, marked by excessive production of collagen which results in hardening and thickening of body tissues. "Deficiency in Fli1 is implicated in the development of systemic sclerosis and hypertensive disorders, which are often accompanied by pronounced fibrosis in different organs." (PMID 36768203, 2023). "FLI1, another predisposing factor in dermal fibrosis and systemic sclerosis, is constitutively downregulated in skin lesions of patients." (PMID 32545915, 2020). "Friend leukemia virus integration 1 (Fli1) deficiency, a predisposing factor of systemic sclerosis (SSc), induces SSc-like phenotypes in various cell types." (PMID 29415756, 2018). "Low FLI-1 expression leads to systemic sclerosis by promoting fibrosis and vascular lesions, to pulmonary arterial hypertension by promoting a local inflammatory state and vascular lesions, and to tumour metastasis by promoting the EndMT process." (PMID 39107790, 2024). "The abnormal expression of FLI-1 in ECs can lead to the occurrence and development of systemic sclerosis (SSc), lupus nephritis (LN), pulmonary hypertension (PAH) and tumours." (PMID 39107790, 2024). "We show here that monocytes from patients with systemic sclerosis have decreased levels of the transcription factor Fli1, and provide new evidence for an antifibrotic role for Fli1 in these cells." (PMID 32508810, 2020). "Constitutively downregulated FLI1 is another influential target in dermal fibrosis and systemic sclerosis." (PMID 32545915, 2020). "Previous studies showed that ERG or FLI1 expression was downregulated in atherosclerosis, systemic sclerosis, pulmonary arterial hypertension, and liver fibrosis." (PMID 30500808, 2018). "With regard to systemic sclerosis, the therapeutic approaches targeting Fli1 are even more limited." (PMID 36768203, 2023). "In contrast to ERG, the function of FLI1 is less-characterized in ECs; its ablation results in upregulation of CTSL and CXCL6 and downregulation of CXCL5 and CCN1 in the context of systemic sclerosis." (PMID 30500808, 2018). "elucidated FLI1’s pivotal role in alloreactive CD4+ T cell activation and differentiation in Graft-versus-host disease, while its involvement in Treg induction in systemic sclerosis has been highlighted in other studies." (PMID 39140108, 2024).
lymphoma (15 papers, 2010 to 2025). A malignant (clonal) proliferation of B- lymphocytes or T- lymphocytes which involves the lymph nodes, bone marrow and/or extranodal sites. "In a mouse model, FLI-1 overexpression resulted in the development of pre-T-cell lymphoblastic leukemia/lymphoma, associated with increased NOT1 expression." (PMID 38280044, 2024). "The major limitation of this study is it lacks molecular characterization of the FLI-1 positive lymphomas." (PMID 38280044, 2024). "The largest study included 132 non-Hodgkin’s lymphoma cases, and 14.4% of the lymphomas demonstrated FLI-1 expression, respectively." (PMID 38280044, 2024). "Further research with a larger cohort will help discover the prognostic value of FLI-1 in lymphomas." (PMID 38280044, 2024). "The CD4, CD8 and TCRβ phenotype of cells in the Fli-1 thymus, liver and lymph node suggested that the disease was a T cell lymphoblastic leukaemia/lymphoma (pre-T LBL)." (PMID 23667468, 2013). "Surprisingly, Fli-1 overexpression in vivo eventuated in development of pre-T cell lymphoblastic leukaemia/lymphoma (pre-T LBL)." (PMID 23667468, 2013). "Molecular studies, such as fluorescence in situ hybridization or next-generation sequencing for FLI-1 translocation, amplification, or analysis of FLI-1 expression level through mRNA level, are needed in the future to elucidate the biology of FLI-1 in lymphomas." (PMID 38280044, 2024). "Interestingly, in the current study, we observed that FLI-1 expression was higher in high-grade or precursor-origin lymphomas than in low-grade lymphomas, such as MALT lymphoma and follicular lymphoma." (PMID 38280044, 2024). "FLI1 also positively regulated genes that are downregulated in lymphoma cell lines exposed to signaling inhibitors such as the PI3K delta inhibitor idelalisib, the BTK inhibitor ibrutinib and the BET Bromodomain inhibitors, while negatively controlling genes upregulated by the same compounds." (PMID 34763718, 2021). "Interestingly, Fli-1 overexpression in vivo eventually resulted in a fatal T cell lymphoblastic leukaemia/lymphoma with infiltration of leukaemic cells into the thymus, spleen, lymph node, bone marrow and liver." (PMID 23667468, 2013). "For example, the detection of FLI1 is relatively specific for EwS, but its specificity is limited by its expression in lymphoblastic leukemias and lymphomas, several soft-tissue sarcomas, and by the fact that around 15% of EwS exhibit variant translocations not involving FLI1." (PMID 33919988, 2021). "However, a lack of knowledge on FLI-1 expression in lymphoma could cause a great deal of detour in the journey to the correct diagnosis." (PMID 38280044, 2024).
primitive neuroectodermal tumor (15 papers, 2010 to 2025). A malignant neoplasm that originates in the neuroectoderm. "In primitive neuroectodermal tumor (PNET), Fli-1 was positive in nuclear." (PMID 24923303, 2014).
Thrombocytopenia (13 papers, 2008 to 2025). A reduction in the number of circulating thrombocytes. "Functional evaluation of germline ETV6 and FLI1 variants from leukemia and thrombocytopenia patients suggests that the substitution of conserved residues disrupts the protein’s general function." (PMID 37377909, 2023). "In man, hemizygous loss of FLI1 results in platelet deficiency and is the cause of Paris-Trousseau/Jacobsen thrombocytopenia." (PMID 33717090, 2021). "FLI1 has tissue restricted expression and deficiency is associated with thrombocytopenia in humans and mice." (PMID 34060252, 2021). "Thrombocytopenia is also a typical characteristic of FLI1 deficiency in Paris-Trousseau/Jacobsen syndrome." (PMID 33717090, 2021). "In humans, Paris-Trousseau syndrome demonstrates the native role of FLI1, whereby the loss of chromosome 11q, the location of FLI1, leads to thrombocytopenia following defects in megakaryocytes." (PMID 31231464, 2019). "Moreover, it was previously shown in mice and humans that mutations in Nfe2, Fli1 and Runx1 cause thrombocytopenia, and that promoter occupancies with NFe2, Fli1 and Runx1 correlated with terminal MK differentiation." (PMID 38067194, 2023). "Mutations in mouse and human Nfe2, Fli1 and Runx1 cause thrombocytopenia." (PMID 27457419, 2016). "Knockout of Fli1 in mice is embryonic lethal, and these mice show vascular abnormalities and thrombocytopenia, pointing to an essential role of FLI1 in endothelial cells and megakaryocytes." (PMID 31231464, 2019). "Much of the current appreciation of the transcriptional control of thrombopoiesis rests on findings in knockout mice and in human pedigrees with syndromic thrombocytopenia, which point separately to three necessary TFs – NF-E2, FLI1 and RUNX1." (PMID 27457419, 2016). "Interestingly, germline pathogenic variants in both TFs co-segregate with autosomal dominant bleeding disorders (i.e., mild thrombocytopenia), although ETV6 also presents a HM risk in ~30% of carriers while FLI1 is most commonly autosomal recessive." (PMID 37377909, 2023). "Several genes responsible for Hermansky–Pudlak, Chediak–Higashi, and Griscelli syndromes have been sequenced, while in forms associated with thrombocytopenia, molecular abnormalities may involve transcription factors such as RUNX1 or FLI1." (PMID 32759727, 2020). "It was suggested that the RUNX1/FLI1 complex negatively regulates ANKRD26 expression and that mutations in 5′-UTR of ANKRD26 disrupt RUNX1/FLI1 inhibition, which would lead to overexpression of ANKRD26 in megakaryocytes and defective proplatelet formation, and thus thrombocytopenia in patients." (PMID 40170493, 2025).